ENSG00000212579
Synonyms: LOC124900228
Gene: Small nucleolar RNA gene on chromosome 6 (35,651,818 to 35,651,945, forward strand). Ensembl gene ENSG00000212579.
Gene Ontology:
Biological process: RNA processing
Cellular component: nucleolus
Homologues: Paralogues in human: SNORA40B (88% identical), SNORA40 (85% identical), SNORA40C (84% identical).